RNU6-361P (RNA, U6 small nuclear 361, pseudogene)
Gene: Small nuclear RNA gene on chromosome 12 (108,926,435 to 108,926,541, reverse strand). Ensembl gene ENSG00000201324.
Homologues: Orthologues: chimpanzee U6 (97% identical), macaque U6 (89% identical), pig U6 (80% identical). Paralogues in human: RNU6-38P (88% identical), RNU6-456P (87% identical), RNU6-1011P (86% identical), RNU6-1042P (86% identical), RNU6-1145P (86% identical), RNU6-29P (86% identical), RNU6-618P (86% identical), RNU6-639P (86% identical), RNU6-891P (86% identical), RNU6-15P (85% identical), RNU6-263P (85% identical), RNU6-331P (85% identical), and 1285 more.